CRP (C-reactive protein)
Diseases named in the same sentence as CRP in open-access papers (continued):
Sharing a sentence is not in itself a finding about the gene and the disease.
cancer (continued). "Besides studies demonstrating consistently an increased risk of mortality due to inflammation and subsequent cancer development, both CRP and IL-6 have also been shown to be associated with non-cardiovascular mortality." (PMID 36742002, 2022). "Therefore, we hold the opinion that the CRP was probably not the cause of cancer itself, but acted as a response marker of environmental risk factors (i.e., smoking, air pollutions, and aging), which can cause chronic low-grade inflammation." (PMID 36117174, 2022). "Patients of GPS 2 with low serum albumin and high CRP levels may be cancer cachexia." (PMID 34519976, 2022). "However, while higher CRP and fibrinogen levels were associated with lower physical activity, they were not independent predictors for cancer mortality in our study." (PMID 35979450, 2022). "High-sensitivity C-reactive protein (hs-CRP), also known as CRP assessed by high-sensitivity assays, is a typical protein produced in response to inflammation, infection, and tissue damage that has been linked to chronic disorders such as cardiovascular disease (CVD) and cancer." (PMID 36407320, 2022). "Previous studies have reported associations between serum CRP concentration and cancers of lung, breast, and colorectal, while showing inconsistent or absent evidences for the associations of other cancer." (PMID 36117174, 2022). "Interestingly, the CRP analysis confirms the inflammatory theory of neoplasm, as statistically significant differences were obtained only in the case of comparisons between the control group and individual stages of cancer." (PMID 35407400, 2022). "In addition, CRP may mediate carcinogenesis and cancer progression via activation of the FcgRs/MAPK/ERK, FcgRs/NF-κB/NLRP3, and FcgRs/IL-6/AKT/STAT3 pathways." (PMID 35847918, 2022). "Furthermore, with the traditional MR and a state-of-the-art non-linear MR, we explored the linear and non-linear relationships between genetically predicted CRP and cancer risk simultaneously." (PMID 36117174, 2022). "In this study, we found that compared with the GNRI, the mGNRI had a better predictive ability for the prognosis of cancer patients and performed better in stratifying the adverse risks of patients, which may be because of the ability of CRP in reflecting systemic inflammation." (PMID 35433784, 2022). "Although we observed three different patterns of non-linear associations between CRP concentration and site-specific cancers risks, obvious inflection points were observed at 3mg/L, and 1mg/L after log-transformed, which were in consistent with the findings for cardiovascular disease." (PMID 36117174, 2022). "CRP exists in multiple isoforms and may act as a mediator of defense response against cancer." (PMID 36361758, 2022). "Various APPs, specifically CRP, may reflect cancer-induced inflammatory processes." (PMID 35174082, 2022). "Therefore, serum CRP levels in patients with cancer might represent the biological behavior of cancer tissues because of the close relationship between IL-6 and CRP." (PMID 36096761, 2022). "Moreover, preoperative CRP level has been proved to be a prognostic indicator for various cancers." (PMID 36684183, 2022). "In addition, the biosensor based on silicon nanowires (SiNW) not only can detect circulating tumours in the blood but can also track the treatment process by determining the C-reactive protein concentrations in the blood of patients with malignant gastrointestinal tumours." (PMID 36109734, 2022). "CRP/Alb, obtained from the combination of CRP and albumin levels, can reflect the inflammation and nutritional status of cancer patients and provide a fully integrated view of the effects of inflammation and low nutritional status on the prognosis of cancer patients." (PMID 36107592, 2022). "Also, using CRP as a prognostic index seems to be more adequate considering the more consistent data associations, as opposed to cancer diagnosis or staging." (PMID 35626439, 2022).
cancer (continued). "Thus, CRP may represent a sensitive surrogate marker of mediators contributing to cancer cell growth and migration." (PMID 34070592, 2021). "Despite decreasing CRP after antibiotic administration, procalcitonin levels remained high for several days and the remarkable difference was observed in the change of blood concentration between procalcitonin and CRP, suggesting the possibility of procalcitonin production by malignant tumors." (PMID 33566306, 2021). "Furthermore, the plasma concentration of CRP is moderately increased in cancer." (PMID 34436973, 2021). "If validated in further studies, determination of the pre-treatment CRP level could be a relevant additional component in clinical practice in order to estimate the potential surgical procedure and to provide a more tailored cancer treatment." (PMID 34070592, 2021). "Hence, we determined the predictive value of CRP and albumin (alone or combined) in older cancer patients and determined whether these biomarkers added value to a clinical prognostic model." (PMID 34944774, 2021). "Our present results showed that routinely measured inflammatory biomarkers (albumin and CRP) and combinations thereof (the GPS, the mGPS, and the CRP/albumin ratio) were respectively and independently associated with one-year mortality in older cancer patients." (PMID 34944774, 2021). "For instance, cancer growth and tumor-host cell interaction could increase CRP levels." (PMID 33685417, 2021). "Previous studies have shown that FDG uptake by the BM is increased in several types of cancer and that it correlates with the levels of serum cytokines, C-reactive protein, and other hematologic parameters, which may be indicative of the BM activation in response to tumor-associated inflammation." (PMID 34108552, 2021). "Cancer-related inflammation has been dubbed the 7th hallmark of cancer, and the systemic inflammatory response (SIR) is measured using cellular (whole white cell counts, neutrophils, lymphocytes, and platelets), and humoral (C-reactive protein (CRP) and albumin) components." (PMID 32865623, 2021). "Similarly, C-reactive protein levels were significantly higher in the cancer group." (PMID 35087747, 2021). "The routinely and easily accessible NLR, LLR, PLR, MLR and CRP/Alb had independent prognostic impact in addition to the established GPA, suggesting that also in the advanced event of BM, flourishing systemic inflammatory processes are negatively associated with the course of cancer disease." (PMID 33473170, 2021). "In addition, CRP can also be considered to assess the prognosis of cancer patients." (PMID 34950214, 2021). "Finally, a dose-effect correlation between elevated hs-CRP levels and prognosis shows that hs-CRP could be valuable in predicting prognosis in advanced cancer patients." (PMID 34711013, 2021). "However, a CRP/PCT value above 95 is in favor of cancer-related fever." (PMID 33777975, 2021). "In addition, both elevated CRP (HR = 0.88; 95% CI: 0.53–1.45) and fibrinogen (HR = 1.001; 95% CI: 1.00–1.003) levels were not independently associated with cancer mortality." (PMID 34210304, 2021). "Elevated levels of CRP are used as an important indicator for the possibility of cardiovascular disease, and the high CRP concentration due to chronic inflammation may affect the cancer development process." (PMID 33925825, 2021). "As previously confirmed, insulin not only influences malignant cancer cells promotion directly via some signaling pathways, but also induces carcinogenic effects indirectly through production of some inflammatory cytokines such as interleukin-6 (IL-6) and C-reactive protein (CRP)." (PMID 34271937, 2021). "In conclusion, we found that two routinely measured inflammatory biomarkers (albumin and CRP) and the scores calculated therefrom (the GPS, the mGPS, and the CRP/albumin ratio) add prognostic value to conventional demographic, oncologic or frailty risk factors when considering older cancer patients." (PMID 34944774, 2021).
cancer (continued). "However, it has to be reminded that serum CRP levels might be influenced by several other variables such as cancer, connective tissue disorders, nutritional status, and drugs." (PMID 34178693, 2021). "Furthermore, the magnitude of the increase in CRP concentrations has been shown to be associated with poorer survival in cancer patients, independent of performance status, weight loss, tumor stage, and other high‐risk pathological features." (PMID 34585050, 2021). "In addition, it indicates the greater importance that anti-inflammatory drugs may have in lowering cancer mortality perhaps in subgroups with low income and high C-reactive protein levels." (PMID 33243216, 2020). "Recently, numerous studies have revealed that inflammatory markers such as C-reactive protein (CRP), erythrocyte sedimentation rate (ESR), and neutrophil/lymphocyte ratio (NLR) are also significantly associated with tumorigenesis and affect the survival of a great number of cancers 26-28." (PMID 32201511, 2020). "This may suggest that CRP reflects tumor aggressiveness and systemic dissemination of cancer cells." (PMID 33351844, 2020). "However, when they performed an instrumental variable analysis, it did not provide evidence for a causal link of CRP concentrations with cancer risk." (PMID 31936330, 2020). "However, there is no consensus regarding the underlying mechanism of CRP increment in patients with (advanced) cancer." (PMID 31936329, 2020). "The results suggest that a protein panel of the inflammatory biomarkers YKL-40, IL-6, and CRP, and the cancer biomarkers CEA and CA19-9 might identify patients that benefit from more aggressive treatment and surveillance, although the additional value of IL-6 and CRP in this aspect is limited." (PMID 32756596, 2020). "Finally, apoB/apoA-I, but not apoB, was a better predictor of cancer death than inflammatory markers (CRP) and other investigated traditional cardiometabolic risk factors." (PMID 31936330, 2020). "Additionally, many cancer cells produce CRP and it can also be difficult to pinpoint whether increase of CRP happens prior to the occurrence of cancer cells." (PMID 33256656, 2020). "Taking this diversity in the physiologic activity of CRP isoforms into account in the context of cancer may give further insight into the relationship between inflammation and cancer and, moreover, improve the clinical evaluation of cancer progression using this biomarker in patient assessment." (PMID 33324413, 2020). "Since a high-CRP level and a low-ALB level both have been found to be associated with poor survival in cancer patients, they might represent an aggressive propensity of the cancer and thus might serve as a factor for risk stratification." (PMID 31998420, 2020). "Additionally, C-reactive protein (CRP) and interleukin 6 (IL-6), other serum inflammatory markers, have shown their possibilities as posttreatment prognostic monitoring factors for predicting the risk of cancer recurrence and patient death." (PMID 32300189, 2020). "For TTS, CRP ≥ 100mg/dL, elevated IL‐6, ≥ 2 organ comorbidities and decreased lymphocyte counts, were selected via univariate analyses as possible relevant prognostic factors: after variable selection, an adjusted HR = 0.87 for cancer patients was observed (95% CI: 0.46‐1.65, P = .67)." (PMID 32931637, 2020). "Furthermore, the predictive value of the apoB/apoA-I, but not apoB, to detect cancer death risk was better than CRP." (PMID 31936330, 2020). "The clinical studies assessing CRP levels in cancer reviewed above, in light of preclinical data regarding the molecular activity of CRP and its distinctive isoforms in the inflammatory microenvironment, may provide invaluable insight into the contribution of CRP to disease progression of cancers." (PMID 33324413, 2020).
cancer (continued). "Finally, although the three GPSs were used in this study, the cutoff values of the CRP and albumin levels were derived from cancer patients, which may lead to their failure to achieve an optimal predictive value for AMI." (PMID 32355581, 2020). "However, the level of circulating leucocytes is not the only parameter that demonstrates a prognostic value in cancer patients: C-reactive protein (CRP) is an acute phase protein produced by the liver in response to activation of macrophages and T-lymphocytes during local and systemic inflammation." (PMID 33096884, 2020). "CRP was positively associated with mortality in NSCLC patients regardless of cancer stage." (PMID 31148582, 2019). "Uric acid has been found to induce the expression of several inflammatory mediators (such as monocyte chemoattractant protein-1 and C-reactive protein), which may lead to a microenvironment with low-grade inflammation, thus favoring transformation into cancer cells." (PMID 32159639, 2019). "Although elevated CRP is not in itself a biomarker of cancer, it may serve as a co‐factor to increase the diagnostic accuracy of other biomarkers in detecting cancer." (PMID 30411459, 2019). "Notably, the association between CRP and death varied obviously with age and tumor type, whereas in the stratified analyses of cancer stage and other characteristics, the trend did not have much fluctuation." (PMID 31148582, 2019). "Thus, serum CRP concentration might be elevated due to hepatic stimulation by cancer-cell-derived inflammatory cytokines." (PMID 31817109, 2019). "Therefore, CRP might be used as an adjunct to other serum biomarkers to improve our ability to diagnose cancer in dogs." (PMID 30411459, 2019). "Lastly, it is possible that unexplained high CRP levels in otherwise healthy people may indicate a later risk of developing cancer (and not just cardiovascular disease)." (PMID 30138391, 2018). "Furthermore, CRP measurement is a low-cost and rapid approach and can be performed conveniently, potentially leading to significantly improved outcomes related to the timing of cancer therapies." (PMID 30097610, 2018). "Thus, an increasing number of studies have revealed elevated levels of CRP in cancer." (PMID 30539028, 2018). "CRP is a nonspecific exponent of the inflammatory process, also caused by cancer." (PMID 29844872, 2018). "Since CRP is biomarker of immune system activity, and CRP concentrations exhibit low values in healthy subjects, the ability to forecast CRP trends might potentially guide clinical decisions in cancer therapies based on the inflammatory state existing in the patient at the precise time of treatment." (PMID 30400835, 2018). "However, the direct link between CRP and cancer is still a debatable topic." (PMID 30539028, 2018). "Therefore, we hypothesized that in combination with CRP, which reflects inflammation and poor survival of cancer patients, ApoA-1 may be a potent prognostic indicator in HCC patients." (PMID 30486825, 2018). "Cancer-related inflammation has been termed the 7th hallmark of cancer, and the systemic inflammatory response (SIR) measured using cellular (whole white cell counts, neutrophils, lymphocytes, and platelets) and humoral [C-reactive protein (CRP) and albumin] components." (PMID 29234999, 2018). "Therefore, cancers often occur along with increased CRP levels." (PMID 29568406, 2018). "Regardless of whether CRP or mCRP were used, higher levels were associated with increased mortality where survival was time from cancer diagnosis to death." (PMID 30138391, 2018). "In addition, participation in mindfulness training leads to a shift from proinflammatory response in cancer patients 33 and a pilot study has suggested that improvements in well‐being following MBSR was associated with increased NK activity and decreased CRP levels." (PMID 28421677, 2017).
cancer (continued). "Accompany with the advancement of laboratory measurements, some experts have suggested that a lower threshold for CRP (cutoff value: 3 mg/l) may enhance the prognostic value of the mGPS in cancer patients, and a high-sensitivity mGPS (HS-mGPS) has been proposed." (PMID 29245945, 2017). "Thus, the aim of the present review was to provide a summary of the relationships between MBIs (MBSR is the most frequently used protocol but not the only one) and biomarkers (focused on cytokines, neuropeptides and CRP) both in healthy individuals and in cancer patients." (PMID 28231775, 2017). "Furthermore, there was a significant positive correlation between the BNP and CRP levels in the cancer patients, which suggested that the plasma BNP levels may have been elevated due to cancer-related inflammation." (PMID 28570595, 2017). "Besides, the CAR, which consists of serum CRP and serum albumin, may indicate not only inflammatory condition but also nutritional status of cancer patients." (PMID 27823974, 2017). "More recently, a novel combination model of CRP and albumin—CRP/Alb ratio—has also been increasingly appreciated since it could serve as a predictor of a clinical outcome in patients with serious infectious disease and those with cancers." (PMID 28676731, 2017). "Finally, to account for competing risks, we ran Fine and Gray regression to estimate cumulative mortality of cancer over time with levels of leptin or CRP as the predictor variable and deaths from major cardiovascular diseases and other causes as competing outcomes." (PMID 26632325, 2016). "However, we observed different effects between leptin and CRP levels on cancer mortality." (PMID 26632325, 2016). "Recently, retrospective and prospective studies in diverse populations have examined the association between cancer susceptibility and CRP SNPs13, 14, 15, with two non-synonymous polymorphisms (+942G>C, dbSNP ID: rs1800947; 1846C>T, dbSNP ID: rs1205) most extensively studied." (PMID 26912098, 2016). "C-reactive protein (CRP), Glasgow prognostic score (GPS), neutrophil-lymphocyte ratio (NLR), platelet-lymphocyte ratio (PLR), lymphocyte-monocyte ratio (LMR), and neutrophil-platelet score (NPS) have been shown to be independent risk factors in various types of malignant tumors." (PMID 28008988, 2016). "Before surgery, CRP levels within the normal range (≤5.0 mg/l) were observed in only 19 out of the 75 (25%) CD patients (group A), in 8/50 (16%) patients undergoing appendectomy (group B) and in 22/50 (44%) patients undergoing right colectomy for cancer (group C)." (PMID 27551522, 2016). "Our findings therefore indicate that the associations between leptin or CRP and cancer may be unique and do not resemble the additive effects observed with cardiovascular disease." (PMID 26632325, 2016). "Similar to our findings using individual biomarkers, a recent analysis within the European Prospective Investigation of Cancer (EPIC)-Norfolk cohort demonstrated an association between CRP and cancer mortality although it was not significant when other confounders were taken in account." (PMID 26860264, 2016). "Moreover, CRP might be directly involved in cancer-related wasting since it has been shown to exacerbate tissue injury of ischemic necrosis in heart attack and stroke." (PMID 26504362, 2015). "CRP kinetics may predict survival, recurrence and clinical course in cancer." (PMID 26717416, 2015). "Therefore, serum CRP level of cancer patients could be an indirect indicator of cancer related inflammation." (PMID 26235332, 2015). "This is noteworthy that abundances of C-reactive protein and angiogenin generally upregulated in cancers samples further increased in metastatic samples, while abundances of carbonic anhydrase 1 generally downregulated in cancer samples further decreased in metastatic samples." (PMID 26376850, 2015).